HDAC4 (histone deacetylase 4)
Diseases named in the same sentence as HDAC4 in open-access papers (continued):
Sharing a sentence is not in itself a finding about the gene and the disease.
cancer (135 papers, 2006 to 2026). A tumor composed of atypical neoplastic, often pleomorphic cells that invade other tissues. "Among them, HDAC4, a member of the class IIa histone deacetylases, exhibits nucleocytoplasmic shuttling, is implicated in various cancers, and is involved in histone deacetylation leading to transcriptional repression." (PMID 38473392, 2024). "Additional miRNAs implicated in the control of HDAC4 mRNA stability in cancer cells are miR-145-3p and miR-145-5p." (PMID 36762207, 2023). "NRF2 signaling in cancer cells attenuates the expression of miR-1 and miR-206 by promoting the expression of HDAC4, causing a shift in glucose metabolism to the pentose phosphate pathway (PPP)." (PMID 36762207, 2023). "Certainly, interfering with HDAC4 levels using RNAi, increases cancer cell susceptibility to different apoptotic stimuli or cellular stressors." (PMID 36762207, 2023). "Recently, the tumor suppressor gene breast cancer type 1 BRCA1-associated protein 1 (BAP1) was shown to antagonize HDAC4 activity to reduce proliferation." (PMID 36762207, 2023). "Altogether, these data support each other and suggest that HDAC4, according to its expression level and/or mutational status, high vs. low or mutated, dictates in part the sensitivity of cancer cells towards chemotherapy and overall survival." (PMID 31703394, 2019). "According to some reports, HDAC4 can regulate the growth and proliferation of cloned cancer cells and is associated with the pathogenesis of hepatocellular carcinoma." (PMID 31552187, 2019). "HDAC4 has been previously implicated in proliferation, cell cycle progression, apoptosis, angiogenesis and differentiation of cancer cells." (PMID 27295551, 2016). "A later study showed that HDAC4 became associated with Sp1 at the proximal p21 promoter, and promoted cancer cell growth via repression of p21 in an Sp1-dependent manner." (PMID 26441331, 2015). "As a member of group II HDACs, HDAC4 is closely linked to many disease processes—including cancer, leukemia, diabetes, infection, and cardiac disease —and is also highly expressed in the brain where it plays an important role in brain functioning." (PMID 25557107, 2015). "However, most HDAC4 inhibitor research and associated clinical trials largely focus on cancer treatment." (PMID 35814270, 2022). "The over-expression of HDACs such as HDAC4 has been associated to pathologies including cancer." (PMID 32493210, 2020). "It has previously been shown that HDAC1, HDAC3, and HDAC4 might be associated with resistance to chemotherapy and poor prognosis in cancer patients." (PMID 26683361, 2016). "Among these, CpG sites associated with ZNF667, TEAD1, HDAC4, MSI2, and CCM2 were predominantly hypermethylated, while malignant tumors overall exhibited lower methylation levels compared to the benign group." (PMID 41597272, 2026). "LMK235 was originally synthesized to inhibit both HDAC5 and HDAC4, and thus, we cannot exclude the possibility that its anti-cancer effects involve inhibition of endogenous HDAC4 activity." (PMID 40290805, 2025). "Together, these findings suggest that chromatin accessibility at the YAP promoter is reduced in cancer cells treated with HDAC4 or pan-HDAC inhibitors." (PMID 41281751, 2025). "In this study, we found that HDAC4 is degraded by the proteasome in cancer cells with impaired DNA repair by homologous recombination and after oxaliplatin (OXPT) treatment." (PMID 41174352, 2025). "TMP269, a class IIa HDACi (HDAC4/5/7/9), has made significant progress in the study of cancer, neurological disorders, and kidney injury." (PMID 39840984, 2025). "Inhibition of HDAC4 reduces migration of cancer cells and decreases the mRNA and protein levels of transcription factor MYB Proto-Oncogene Like 1 (MybL1) and YAP." (PMID 41281751, 2025).
cancer (continued). "In conclusion, our data suggest that the alterations in HDAC4, observed in different cancer types, should also be considered in terms of defects in the DDR and consequent potential combinatorial therapeutic interventions." (PMID 38874468, 2024). "Specifically, MET encodes a receptor tyrosine kinase that is implicated in cell proliferation and frequently overexpressed in various cancers, and HDAC4 (Histone deacetylase 4) influences chromatin structure and regulates cancer proliferation and progression." (PMID 39336170, 2024). "These miRNAs inhibit TKDT and G6PD genes, and their repression by histone deacetylase 4 (HDAC4) through NRF2 supports cancer cell growth." (PMID 38247494, 2024). "While class I HDAC family members (HDAC1/2/3/8) were positively associated with cancer stemness across most of the tested tumor types, class IIA HDAC members (HDAC4/5/7/9) exhibited an inverse correlation." (PMID 39063083, 2024). "HDAC4 is known to interact with various transcription factors, influencing cancer progression and potentially serving as a therapeutic target." (PMID 39336170, 2024). "In several CRISPR-based screenings performed in different cancer cell lines, HDAC4 emerges frequently as a significative hit required for cell fitness." (PMID 36762207, 2023). "In hepatocarcinoma cell lines miR-200a and miR-22 downregulate HDAC4 and their expression negatively correlates with cancer proliferation and migration, suggesting their role as tumor suppressors." (PMID 36762207, 2023). "We were able to demonstrate that class IIa HDAC inhibition reduces the growth of cancer cells with increased HDAC4 expression in vitro and in vivo (CAM model)." (PMID 36982651, 2023). "HDAC4, located on chromosome 2q37.2, is a member of class IIa family of HDACs which are hotspots in the field of cancer drug development." (PMID 37843550, 2023). "Although the pro-oncogenic role of HDAC4 in cancer is known, conditions under which HDAC4 activities antagonize the transformation process are conceivable." (PMID 36762207, 2023). "Although cancer genome projects have allowed us to explore the degree of dysregulation of several genes, including HDAC4 in tumors, we have yet to gain information about the molecular complexity of the protein and its partners." (PMID 36762207, 2023). "Before discussing possible contributions of HDAC4 to cancer development and aggressiveness, we will review some basic concepts about HDAC4." (PMID 36762207, 2023). "In conclusion, although there are several data confirming a role of HDAC4 in cancer cell survival, the mechanism seems to vary from case to case." (PMID 36762207, 2023). "In several cultured cancer cell lines, HDAC4 shows a prominent cytoplasmic localization being actively exported from the nuclei." (PMID 36762207, 2023). "Here we will discuss HDAC4, a member of the class IIa family, and its possible contribution to cancer development." (PMID 36762207, 2023). "Other miRNAs involved in the control of HDAC4 mRNA stability in cancer cells are miR-145-3p and miR-145-5p." (PMID 36762207, 2023). "Our results suggest potentially critical roles of hydroxymethylation of CpGs located within the gene body regions in regulating the gene expression of critical cancer genes, like HDAC4 and IGF1R." (PMID 36909536, 2023). "The aim of this manuscript is to provide an updated overview of the recent progresses regarding the contribution of the epigenetic regulator HDAC4 to cancer development." (PMID 36762207, 2023). "The increased proliferative capacity of tumors is due to alterations in the normal regulation of the cell cycle, and the contribution of HDAC4 to cell cycle progression has been observed in various contexts, including normal cells and different cancer models." (PMID 36762207, 2023).
cancer (continued). "Nuclear factor erythroid-2 related factor-2 (NRF2) signaling in cancer cells attenuates miR-1 and miR-206 expression by promoting the expression of HDAC4, thus inducing a shift of glucose metabolism towards the pentose phosphate pathway (PPP)." (PMID 36762207, 2023). "Although plausible, the epigenomic mechanism does not exclude additional tasks, which independently form chromatin and DNA accessibility, are dysregulated in cancer cells in a HDAC4-dependent manner." (PMID 36762207, 2023). "Aberrant HDAC4 expression has been correlated with multiple biological processes in cancers, including tumorigenesis, migration, and drug resistance." (PMID 37711168, 2023). "The second part (Chapter 5) is dedicated to HDAC4 in cancer, discussing the current state of research in hematological and solid tumors and considering the principal hallmarks of cancer." (PMID 36762207, 2023). "Histone deacetylase 4 (HDAC4) has been shown to be involved in cell proliferation, differentiation, and migration and is associated with a variety of cancers." (PMID 35847036, 2022). "A closer look at these factors identified a group of three histone deacetylases (Hdac4, Hdac7, Hdac8) with reported implications in cancer patient's prognosis and with a wide range of available specific inhibitory compounds." (PMID 35016723, 2022). "HDAC4 plays global roles in the regulation of gene transcription, cell growth, survival, and proliferation, and aberrant expression of HDAC4 activity leads to cancer development." (PMID 36703926, 2022). "The overexpression of HDAC4 decreased the expression of miR-200b, which led to the resistance of lung cancer cells to anti-cancer drugs." (PMID 35682560, 2022). "HDAC4 and HDAC10 are Class II HDACs, which are associated with proliferation, migration, and invasion of a variety of cancers." (PMID 36172179, 2022). "Histone deacetylase 4 is a critical regulator of various biological processes, including inflammation, T cell differentiation, and malignant behavior of cancer cells; thus, previous studies have reported the role of HDAC4 as a biomarker in multiple diseases." (PMID 35602496, 2022). "HDAC4 signaling contributes to several cancer phenotypes, including increased proliferation and suppression of differentiation transcriptional programs." (PMID 35118387, 2022). "Class IIa HDAC-4 stained 44% of benign and 36% of malignant tumors, mostly with a nuclear pattern, while 4 cases (different from the ones mentioned for HDAC-2) showed a cytoplasmic pattern of staining (3 PAs and 1 SCC)." (PMID 33799478, 2021). "Several nephrological and neurodegenerative diseases, as well as cancer types like breast cancer are related to HDAC4 making the protein an attractive drug target." (PMID 34681256, 2021). "Within VHL-positive cancer cell lines, HDAC4 inhibition by shRNA increases HIF-1α protein acetylation levels, while HDAC4 overexpression decreases HIF-1α acetylation levels." (PMID 33109235, 2020). "In the previous reports, the relationship of HDAC4 and Hif1α was investigated in cancer cell lines or for tumor angiogenesis." (PMID 32354322, 2020). "Other concomitant events should be checked to indicate the specific physiological effect of PRL-3 and HDAC4 in the cancer cell state transition." (PMID 31887658, 2020). "The Cancer Genome Atlas (TCGA) dataset analysis revealed that HDAC4, HDAC7 and HDAC9 as well as HDAC class I members HDAC1 and HDAC2 is significantly correlated with patient survival." (PMID 31635225, 2019). "To this end, we performed a microarray analysis to identify genes deregulated by cisplatin in cancer cells and identified HDAC4 as a gene inhibited by cisplatin." (PMID 31703394, 2019). "Five HDAC genes (HDAC2, HDAC4, HDAC5, HDAC10, and SIRT3) showed copy number loss in at least two cancer types." (PMID 30760718, 2019). "We analyzed the cisplatin pangenomic response in cancer cells and found HDAC4 as a major epigenetic regulator being inhibited." (PMID 31703394, 2019).
cancer (continued). "Cancer cells promote nuclear translocation of HDAC4 by increasing endogenous antioxidants, which decreases miR-206 expression through deacetylation of its promoter and promotes cancer progression." (PMID 31717786, 2019). "Meanwhile, we focused on the regulative effect of MALAT1 working on HDAC4—a proliferation and apoptosis‐related factor in manifold cancers." (PMID 30094957, 2018). "According to previous researches, HDAC4, which was targeted by multiple miRNAs, was involved in proliferation and apoptosis in various malignant tumors including OS." (PMID 30094957, 2018). "Inhibition of cell growth and induction of apoptosis by HDAC4/5 inhibition using LMK-235 has been reported for different cancer cell lines as well as chemoresistant cancer cell lines." (PMID 30321986, 2018). "More importantly, histone deacetylase 4 (HDAC4), known to have critical roles in cancer development, was shown to be directly targeted and regulated by miR-22." (PMID 27119349, 2016). "Consistent with the many reports on tumor-progressing role of HDACs, HDAC4 has been reported to be tumorigenic in different human cancers." (PMID 26206152, 2015). "HDAC4 has been proposed to contribute to cisplatin resistance of cancer cells by promoting STAT1 deacetylation." (PMID 25504437, 2015). "Early study found that overexpression of HDAC4 increases cell growth and tumor development by repressing p21CIP1 in cancer." (PMID 25504437, 2015). "Previous studies have demonstrated that the class I and II histone deacetylases (HDACs), including HDAC1, HDAC2, HDAC3 and HDAC4, repress p21 expression in multiple human cancers." (PMID 26098774, 2015). "Experiments performed on cancer cell lines revealed the ability of SAHA to induce the degradation via RANBP2-mediated proteasome of both HDAC4 and HDAC5 in vitro." (PMID 25759639, 2015). "EZH2 activation and HDAC4 activation correlate with growth factor signaling and inflammation, respectively, and represent two distinct states for cancer cells." (PMID 24079712, 2013). "Further studies are needed to elucidate the mechanisms for the mutual exclusiveness of EZH2 and HDAC4 and to determine therapeutic targets for the distinct epigenetic-specific cancer phenotypes." (PMID 24079712, 2013). "Recently it has been found that SAHA can also promote the degradation of HDAC4 and possibly other class IIa HDACs at the protein level in various cancer cell lines." (PMID 22140466, 2011). "Both HDAC2 and HDAC4 were chosen for this study because the work of others has revealed abnormal levels of these proteins in many types of cancer." (PMID 21507255, 2011). "In the 330 predicted conserved targets, we found that human HDAC4, known to have critical roles in cancer development by repressing differentiation-promoting genes, contained putative conserved miR-22 target site." (PMID 20842113, 2010). "Considering the importance of T-cell inflamed TME gene signatures driving TILs, as well as the potential impact of HDAC4 in regulating cancer growth and tumor immunity, the delineation of molecular mechanisms leading to reduced antitumor immune responses is of utmost significance." (PMID 40361444, 2025). "HDAC4 serves crucial roles in chromatin maintenance and function by modulating histone acetylation, its dysregulation has frequently been observed in human cancers." (PMID 38297362, 2024). "In this cancer cell line, only HDAC4 silencing resulted in RS." (PMID 38874468, 2024). "Furthermore, despite the known involvement of histone deacetylases (HDACs) in cancer development and progression, the potential relationship between Sox2 and HDACs, particularly HDAC4, in CRC has received little study." (PMID 38473392, 2024). "Genetic alterations of HDAC4 in cancer mainly contemplate an increase in its expression level." (PMID 36762207, 2023).
cancer (continued). "In gastric tumor, low expression of miR-206 is associated with a better prognosis, suggesting a potential inhibitory role of this miRNA in cancer progression and this tumor-suppressor action is supposedly mediated by the inhibition of a plethora of target genes, including HDAC4." (PMID 36762207, 2023). "HDAC4 is frequently amplificated or overexpressed in cancer specimens and cell lines." (PMID 36762207, 2023). "The dysregulation of HDAC4 in cancer could also involve the control of its subcellular localization as the result of alterations in cell signaling." (PMID 36762207, 2023). "It is possible that specific oncogenic transformations make cancer cells addicted to HDAC4." (PMID 36762207, 2023). "HDAC4 is required for the proliferation and survival of different cancer cells." (PMID 36762207, 2023). "HDAC4 is aberrantly expressed in a variety of cancer cells and tissues and may play a role in cancer development." (PMID 35252174, 2022). "HDAC4 inhibitors have been proved effective for cancer, CVDs, and neurodegeneration." (PMID 35814270, 2022). "Some studies support our results, showing that increased expression of autotaxin in PCa cell lines is mediated by the downregulation of HDAC7 and HDAC3; additionally, HDAC5 is downregulated in human cancer, namely PCa, and decreased expression of HDAC4 increases the growth of PCa cells." (PMID 34833128, 2021). "Similarly, it is very likely that there are multiple downstream mediators of HDAC4, which play important roles in the overall effects of HDAC4 in cancer development in vivo." (PMID 34359722, 2021). "HDAC4 is recruited to the nuclei of HR cancer cells, where it may exert an inhibitory effect on differentiation and contribute to the development of the aggressive phenotype of late stage CaP." (PMID 34150649, 2021). "However, this was inconsistent with the previous reports, in which Ablating HDAC4 signaling induced Hif1α protein acetylation, reduced Hif1α protein level in cancer cell lines, and inhibited endothelial tumor angiogenesis." (PMID 32354322, 2020). "The studies presented that HDAC4 played an important role in hypoxic induced angiogenesis, and that pharmalogical inhibition and shRNA against HDAC4 offered a new strategy in anti-cancer therapy through decreasing HIF-1α expression and inhibiting angiogenesis in tumor." (PMID 32354322, 2020). "Among all 169 potential cancer drivers, 33 genes, including Notch1, Jup and Met, showed oncogenic features, whereas the majority of genes, including Lipc, Cntn5, Hdac4, Nrxn3 and Cntnap5c, exhibited tumour suppressor features." (PMID 32591500, 2020). "In addition to cancer, the role of HDAC4 has been extensively studied in the context of neurodegenerative diseases." (PMID 31067680, 2019). "Many studies have indicated that HDAC4 can contribute to the progression of different cancers." (PMID 31552187, 2019). "Although these data suggest that in general, increased HDAC4 expression could be a resistance mechanism in different types of cancers and to several sorts of chemotherapeutic drugs, it is clearly not always the case." (PMID 31703394, 2019). "Indeed, we were able to co-immunoprecipitate HDAC4 and Nup155 confirming an interaction of both proteins also in liver-derived cancer cells." (PMID 31089132, 2019). "HDAC4 expression was tested by Western blotting with 10 cancer tissues and paired normal tissues." (PMID 30131570, 2018). "Many previous studies have been done on the biological functions of HDAC4 in cancer." (PMID 27295551, 2016). "The clinical significance of HDAC4 in cancers is relatively less well investigated." (PMID 27295551, 2016). "HDAC4 is particularly important for cancer development and progression." (PMID 27295551, 2016). "Furthermore, HDAC4 also promotes development and progression of cancer independently of its chromatin-regulatory function." (PMID 27295551, 2016).